IL12B (interleukin 12B)
Diseases named in the same sentence as IL12B in open-access papers (continued):
Sharing a sentence is not in itself a finding about the gene and the disease.
pulmonary tuberculosis (3 papers, 2011 to 2013). A bacterial infection that affects the lungs and is caused by Mycobacterium tuberculosis. "We examined whether polymorphisms in interleukin-12B (IL12B) associate with susceptibility to pulmonary tuberculosis (PTB) in two West African populations (from The Gambia and Guinea-Bissau) and in two independent populations from North and South America." (PMID 21339808, 2011). "The purpose of this study was to examine whether polymorphisms in the IL12B gene were associated with susceptibility to pulmonary tuberculosis in two West African populations – from The Gambia and Guinea-Bissau – and to replicate these findings in independent samples from North and South America." (PMID 21339808, 2011). "Therefore, the aim of this study was to verify if IFNG, IL12B, TNF, IL17A, IL10, and TGFB1 gene polymorphisms influence the immune response of Brazilian patients with pulmonary tuberculosis (PTB) at different time points of antituberculosis treatment (T1, T2, and T3)." (PMID 23634300, 2013).
sarcoidosis (3 papers, 2018 to 2022). Sarcoidosis is a multisystemic disorder of unknown cause characterized by the formation of immune granulomas in involved organs. "In a large GWAS study, six polymorphisms of IL12B yielded a significant association with sarcoidosis and one of them (rs4921492) more specifically with central nervous system involvement." (PMID 32823753, 2020). "A population of activated DCs that produced IL12B were present almost exclusively in the sarcoidosis samples." (PMID 35668129, 2022). "As for Rac1 mediators, we can hypothesize that genetic variations observed in IL17 receptors and/or in IL12B, encoding the common p40 subunit of IL12 and IL23, could disturb the expression of IL17 and be a predisposing state for sarcoidosis." (PMID 32823753, 2020).
Sepsis (3 papers, 2023 to 2025). Sepsis is defined as life-threatening organ dysfunction caused by a dysregulated host response to infection. "Notably, iNP‐SAHA significantly reduced Il‐12b expression by 18.3‐fold, which was upregulated in LPS‐stimulated primary macrophages, and has been observed in a polymicrobial murine model of abdominal sepsis and human sepsis." (PMID 38193117, 2024). "While IL‐12B and CXCL‐1 levels were higher in sepsis DM mice compared to DM‐only mice, these differences were not statistically significant." (PMID 40654181, 2025). "In our model, septic DM mice exhibited trends toward elevated levels of pro‐inflammatory markers, including IL‐12B, CXCL‐1, and TNF‐α, and reduced IL‐4 levels compared to mice with sepsis or DM alone; however, these differences did not consistently reach statistical significance." (PMID 40654181, 2025).
Takayasu arteritis (3 papers, 2017 to 2021). A rare inflammatory large-vessel vasculitis primarily affecting the aorta and its major branches, but also other large vessels, causing stenosis, occlusion, or aneurysm. "A previous study revealed the association between susceptibility to Takayasu arteritis (TAK) and a single nucleotide polymorphism (SNP) rs6871626 located in IL12B, which encodes interleukin (IL)-12p40, a common component of IL-12p70 and IL-23." (PMID 28874185, 2017).
type 2 diabetes (3 papers, 2018 to 2024). "IL12B is expressed in the retina (The Ocular Tissue Database) and has been implicated in both type 1 and type 2 diabetes, although there are no prior reports of a role in diabetic eye disease." (PMID 29739359, 2018).
Allergy (2 papers, 2006 to 2021). An allergy is an immune response or reaction to substances that are usually not harmful. "Macrophage engulfed microorganism are leading to IL12p70 production, a heterodimer of IL12p40 (IL12B) and IL12p35 (IL12A), which is a primary inducer of Th1 cell development and a critical factor in the development of allergy." (PMID 16600026, 2006).
Arthritis (2 papers, 2012 to 2026). Inflammation of a joint. "In the present study, integration of genetic and clinical data revealed that IL-12B haplotypes were associated with genital ulcers and arthritis, whereas IL-23R haplotypes correlated with erythema nodosum, pathergy positivity, ocular involvement, and papulopustular lesions." (PMID 41596568, 2026).
autoimmune disorders (2 papers, 2015 to 2017). "Further, the ability of PIF to modulate IL-23 while preserving IL-12B expression (which regulates polarization of T-cells to Th1 phenotype) may explain pregnancy-induced protection against autoimmunity concurrent with preservation of anti-pathogenic responses." (PMID 28423529, 2017).
Behçet’s disease (2 papers, 2014 to 2026). "This study aimed to investigate the association of Interleukin-12B and Interleukin-23R gene polymorphisms and haplotype distributions with Behçet’s disease in Denizli, a province of Turkey." (PMID 41596568, 2026). "The results demonstrated that the Interleukin-12B rs2082412 G allele and rs3213119 G allele were associated with increased risk of Behçet’s disease." (PMID 41596568, 2026). "In conclusion, this study provides evidence supporting an association between IL-12B and IL-23R gene polymorphisms and haplotypes and susceptibility to Behçet’s disease in a Turkish population." (PMID 41596568, 2026). "Our findings highlight the potential functional impact of specific IL-12B and IL-23R variants in the pathogenesis of Behçet’s Disease (BD)." (PMID 41596568, 2026).
Candidemia (2 papers, 2018 to 2020). A form of invasive candidiasis where species of CANDIDA are present in the blood. "In a large prospective cohort of ICU patients with candidemia, polymorphisms in cytokine genes encoding IL-10 and IL12B were found to be associated with persistent candidemia." (PMID 29371502, 2018). "Two polymorphisms, one in IL10 and one in IL12B, are associated with persistent candidemia, but not candidemia in general." (PMID 32185141, 2020).
cardiomyopathy (2 papers, 2014 to 2020). A disease of the heart muscle or myocardium proper. "So, the genetic control of the human susceptibility to cardiomyopathy mainly target genes that are involved in the regulation of this TH1 response, such as IL12B and IL10 genes." (PMID 32733459, 2020).
Chagas cardiomyopathy (2 papers, 2020). A disease of the cardiac muscle developed subsequent to the initial protozoan infection by trypanosoma cruzi. "On the other hand, our data confirmed the involvement of IL12B and IL10 in the control of susceptibility to human Chagas cardiomyopathy." (PMID 32733459, 2020). "IL-12R gene polymorphisms, including IL-12B 3' UTR C and IL-12B 3' UTR CC, result in significantly higher gene expression, and may increase the incidence of Chagas cardiomyopathy." (PMID 32194399, 2020). "Interestingly, these two markers are located 5 to 13 kb away from the rs3212227 polymorphism (IL12B 3′UTR region), that was previously associated to Chagas cardiomyopathy." (PMID 32733459, 2020).
chronic mucocutaneous candidiasis (2 papers, 2018 to 2024). "However, the susceptibility of certain individuals with deficiencies in IL-12B, IL-12Rβ1, or IL-23R to chronic mucocutaneous candidiasis (CMC) indicates the crucial role of human IL-23 in defending against mucocutaneous Candida spp." (PMID 38535546, 2024).
cryptococcosis (2 papers, 2021 to 2024). An acute or chronic, localized or disseminated infection by Cryptococcus neoformans. "The authors first used single-cell RNA sequencing to identify that Batf3-dependent cDC1 exhibited a unique mRNA signature during murine cryptococcosis, strongly upregulating transcripts related to T cell recruitment and Th1 polarization, such as Il12b, Stat4, and Ccl22." (PMID 39254303, 2024).
cyst (2 papers, 2020 to 2024). A sac-like closed membranous structure that may be empty or contain fluid or amorphous material. "We observed that both cyst load and behavior were correlated with the expression levels of interferon-gamma (IFN-γ), interleukin-12b (IL-12b), and tumor necrosis factor (TNF)." (PMID 31940479, 2020).
E. coli infection (2 papers, 2020 to 2025). "A plausible anti-inflammatory effect of EPS was observed in this study, as the expression of the IL12B, TNF, CSF1 and CSF3 genes was abated in the cells pretreated before E. coli infection." (PMID 32234079, 2020).
endometriosis (2 papers, 2024 to 2025). The growth of functional endometrial tissue in anatomic sites outside the uterine body. "Thus, we were able to show that the expression of the M1 macrophage marker genes TNF and IL12B was significantly decreased in the endometriosis foci, and the expression of the M2 macrophage marker gene ARG1 was significantly increased." (PMID 39253270, 2024).
gastric cancer (2 papers, 2020 to 2025). A primary or metastatic malignant neoplasm involving the stomach. "Several identified hub genes, including CXCL1, CCL20, IL12B, STAT4, and CD80, are involved in chemokine signaling, immune modulation, and inflammation, which can promote H. pylori–mediated gastric cancer." (PMID 40445003, 2025).
genital wart (2 papers, 2023 to 2025). "The increased expression of GZMB, IFNG, IL-12B, and IL-8 and the decreased expression of NFATC4 and IL-7 in genital wart samples were highlighted." (PMID 40142865, 2025). "The involvement of T helper 1 (Th1) cells in host defense against HPV was evidenced in this study by the overexpression of CD4, along with overexpression of IFNG, IL12B, and IL8 in genital warts." (PMID 37053156, 2023).
keratitis (2 papers, 2020 to 2022). A corneal disease that is characterized by inflammation of the cornea. "The co-existence of the heterologous minor alleles (OR = 0.32, 95% CI: 0.14–0.71; p = 0.0038) or genotypes (OR = 0.24; 95% CI: 0.1–0.58; p = 0.0018) of IL12B were associated with a significant reduction in the risk of keratitis." (PMID 36422638, 2022). "The current study did not confirm the association of the homozygous dominant genotype in SNP rs3212227 of IL12B with sterile keratitis but did find that associations of two other SNPs in IL12B, SNPs rs2569254 or rs730691, were protective for all cases of keratitis and microbial keratitis." (PMID 36422638, 2022). "Certain SNPs in IL6, CXCL8, and IL12B occurred less frequently in all keratitis cases than in controls." (PMID 36422638, 2022). "A previous study showed that people who carry the IL12B homozygous dominant genotype in SNP rs3212227 were more likely to have had sterile keratitis during contact lens wear than a control population." (PMID 36422638, 2022).
lymphoma (2 papers, 2018 to 2022). A malignant (clonal) proliferation of B- lymphocytes or T- lymphocytes which involves the lymph nodes, bone marrow and/or extranodal sites. "In addition, we observed co-expression of immune mediators, such as interferons and their targets (IFNA1-2, IFNA7-8, IFNB1, and IFNG), as well as proinflammatory cytokines (IL-1B and IL12B) and chemokines and their receptors (CXCL9-11 and CXCR3) by CpG(B)-STAT3dODN-treated lymphoma cells (right)." (PMID 29433938, 2018).
melanoma (2 papers, 2022 to 2024). A malignant, usually aggressive tumor composed of atypical, neoplastic melanocytes. "COMT, SLC6A4, SLC6A3, and IL-12b gene mutations were also associated with melanoma sites and TNM stage, anxiety, and QOL." (PMID 36405903, 2022).
osteomyelitis (2 papers, 2021 to 2024). An acute or chronic inflammation of the bone and its structures due to infection with pyogenic bacteria. "Recent investigations have identified a linkage between variations in the IL-12B gene and various infectious diseases, including chronic hepatitis B, Q fever caused by Coxsackie burnetii, and chronic osteomyelitis." (PMID 39301021, 2024). "However, further research is imperative as the current understanding of the relationship between osteomyelitis and IL-12B polymorphisms remains limited." (PMID 39301021, 2024). "Consequently, polymorphisms in the IL-12B gene may prevent the development of osteomyelitis by modulating serum IL-12 levels and the IL-12/interferon pathway." (PMID 39301021, 2024).
Stroke (2 papers, 2019 to 2020). Sudden impairment of blood flow to a part of the brain due to occlusion or rupture of an artery to the brain. "Moreover, IL12B ∗A/∗A genotype was less frequent in patients with a history of stroke and IL12B ∗A/∗C genotype had increased risk of stroke." (PMID 31186952, 2019).
Thrombocytopenia (2 papers, 2020 to 2026). A reduction in the number of circulating thrombocytes. "In contrast, anti-IFN-γ treatment alone significantly improves hepatosplenomegaly, while single treatment with anti-IFNAR only improves thrombocytopenia and minimizes the expression of inflammatory cytokines (Il6, Il12b, and Tnfa)." (PMID 41561071, 2026). "To summarize, our study demonstrated new associations between SNPs in IL1B, IL12B, IL28B, TLR4 genes and symptoms of cCMV infection such as prematurity, splenomegaly, thrombocytopenia and hepatitis respectively." (PMID 32421725, 2020).
vasculitis (2 papers, 2021). "IL12B or IL12RB1 deficiency and salmonellosis should be considered in MSMD patients with vasculitis." (PMID 34389021, 2021).
acral melanoma (1 paper, 2022). "IL-12 was also negatively correlated with depression in non-acral melanoma with TNM stages 0 and I, and with low QOL in non-acral melanoma TNM stages 0 and I. In addition, the IL-12b gene mutation was significantly associated with a low HADS-A score." (PMID 36405903, 2022).
acute kidney injury (1 paper, 2017). Sudden and sustained deterioration of the kidney function characterized by decreased glomerular filtration rate, increased serum creatinine or oliguria. "ATF3 was demonstrated interacted directly with histone deacetylase 1 (HDAC1) and recruited HDAC1 into the ATF/NF-κB sites in the IL-6 and IL-12b gene promoters to protect against acute kidney injury." (PMID 28912732, 2017).
African trypanosomiasis (1 paper, 2021). "Notable differences were the absence Il12a and Il12b from the rodent brain profiles and the absence of IlIa from African trypanosomiasis ID5143." (PMID 34762691, 2021). "Of the 38 African trypanosomiasis ID5143 pathway genes nine could not be detected including Kng1 and 2 encoding the kallikrein-kinin hormonal cascade in addition to Il12b and the E-selectin gene Sele while the levels Il12a, Apoa1, Fasl and Plcb2 message were subthreshold." (PMID 34762691, 2021).
alopecia areata (1 paper, 2024). Loss of scalp and body hair involving microscopically inflammatory patchy areas. "This systematic review and meta-analysis were done to find the association between rs3118470, rs2275913, rs3212227, and rs10889677 of the IL2RA, IL17A, IL12B, and IL23R genes, respectively, of the interleukin family with alopecia areata." (PMID 38394507, 2024). "Throughout the assessment, 165 articles were not related to Alopecia Areata and IL2RA, IL17A, IL12B IL23R genes, 11 were non-English publications and 5 articles were on animal models." (PMID 38394507, 2024).
Anxiety (1 paper, 2022). Intense feelings of nervousness, tension, or panic often arise in response to interpersonal stresses. "However, the IL-12b gene mutation was significantly associated with anxiety (P = 0.031), and the SLC6A3 gene mutation was significantly associated with low QOL (P = 0.017)." (PMID 36405903, 2022).
aphthous ulcers (1 paper, 2025). "IL23 (subunits encoded by IL12B and IL23A), which is strongly implicated in IBD pathology, fell below the 5 TPM detection threshold, but both transcripts were increased > 5‐fold in aphthous ulcers versus Peyer's patches." (PMID 40386941, 2025).
Ascites (1 paper, 2018). Accumulation of fluid in the peritoneal cavity (between the layers of the peritoneum that lines the abdomen). "From a therapeutical perspective, it might be beneficial to determine genetic predispositions and environmental factors involved in ascites-mediated suppression of IL12B." (PMID 29997615, 2018). "This notion would be consistent with the observed stable IL12B suppression by a prolonged exposure of MDMs to ascites." (PMID 29997615, 2018). "We conclude that suppression of IL12B expression by OC ascites is reversible by ascites withdrawal in principle." (PMID 29997615, 2018). "We speculated that ascites disables translocation and chromatin binding of NFκB effector transcription factors and, in consequence, induction of IL12B transcription." (PMID 29997615, 2018). "Because nuclear translocation of REL and p65 is diminished in the presence of ascites, we speculated that transcription of target genes other than IL12B may be affected." (PMID 29997615, 2018). "Mean H3K27me3 signals at the TSS of IL12B were slightly elevated in MDMs exposed to ascites." (PMID 29997615, 2018). "Unaltered occupancy of REL and p65 at both the IL12B and CXCL10 loci in the presence of ascites strongly suggests that these gene-specific mechanisms do not affect NFκB chromatin binding." (PMID 29997615, 2018). "Surprisingly, in the short-term ascites exposed population, REL and p65 were recruited to a similar extent at the −1,200 bp site of IL12B, while long-term exposure to ascites led to reduced but measurable recruitment." (PMID 29997615, 2018). "Since translocation of REL and p65 is impaired in the presence of ascites, and IL12B mRNA induction is prevented, while that of CXCL10 is not, an obvious hypothesis is that these transcripts are subject to gene-specific regulation." (PMID 29997615, 2018).
atherosclerosis (1 paper, 2024). A disease characterized by the build-up of fatty material and calcium deposition in the arterial wall resulting in partial or complete occlusion of the arterial lumen. "IL12B encodes the shared p40 subunit (IL‐12p40) of IL‐12 and IL‐23, which have diverse immune functions and are closely related to the occurrence and development of atherosclerosis (AS)." (PMID 38189641, 2024).
autoimmune thyroid disease (1 paper, 2012). Inflammatory disease of the thyroid gland due to autoimmune responses leading to lymphocytic infiltration of the gland. "IL12B has been identified to possibly influence the development of autoimmune thyroid diseases and the related ophthalmopathy in male patients in the Western world, but it has not yet been deeply examined in Oriental patients." (PMID 23164360, 2012). "Although the SNPs and expression of IL12B may be associated with autoimmune thyroid diseases, especially GD and GO in Western male populations, a genetic association between IL12B and GO in oriental populations has not been identified." (PMID 23164360, 2012).
avian influenza (1 paper, 2025). Infection of domestic and wild fowl and other birds with influenza A virus. "Immune genes, such as interleukins IL6, IL12B, and IL25, located in the introgressed regions, play a crucial role in the immune response to most low pathogenic avian influenza strains." (PMID 39965774, 2025).
Chronic colitis (1 paper, 2024). A chronic inflammatory disease of the large intestine (colon, cecum and rectum). "The reduction of Il12a, Il12b, and Il23a expression was also observed in chronic colitis." (PMID 39113810, 2024).
chronic granulomatous disease (1 paper, 2025). Chronic granulomatous disease (CGD) is a rare primary immunodeficiency, mainly affecting phagocytes, which is characterized by an increased susceptibility to severe and recurrent bacterial and fungal infections, along with the development of granulomas. "Among them, IL12B and LTA are already established therapeutic targets for PsO, and IFNGR2 has been developed as a therapeutic target for chronic granulomatous disease." (PMID 40564099, 2025).
Co-infection (1 paper, 2021). "Co-infection was associated with increased IL-6 (P = 0.043) and IL-12B (P = 0.017) expression." (PMID 33819170, 2021). "IL-12B is closely related to the cellular response to mycobacterial infections, and its elevation as a result of M. leprae/SARS-CoV-2 co-infection introduces important questions." (PMID 33819170, 2021).